BAP1 (BRCA1 associated deubiquitinase 1)
Diseases named in the same sentence as BAP1 in open-access papers (continued):
Sharing a sentence is not in itself a finding about the gene and the disease.
metastatic disease (continued). "We analyzed BAP1 and PBRM1 loss of protein expression in patient-matched primary and metastatic tumors from 97 patients." (PMID 28327121, 2017). "We evaluated intra-metastatic tumor heterogeneity using 12 patients who had multiple blocks available from the same tumor with representative pathology; 100 and 92% showed concordant BAP1 and PBRM1 expression, respectively." (PMID 28327121, 2017). "Patients with discordant BAP1 or PBRM1 expression across their matched primary and metastatic tumors usually showed loss of expression during progression to metastatic ccRCC." (PMID 28327121, 2017). "Unfortunately, there are currently no specific therapies for metastatic tumors harboring BAP1 mutations." (PMID 40754831, 2025). "There has been increasing attention on the impact of activating genetic mutations in GNAQ and GNA11, loss-of-function mutations in the tumor suppressor gene BAP1, and recurrent mutations at codon 625 of SF3B1 on the advancement of UM towards metastatic disease." (PMID 39061150, 2024). "Germline BAP1 mutation appeared to result in more metastatic disease compared to non-BAP1 carriers (71.4% vs. 18.0%) in a small comparison between 7 germline BAP1 UM and 455 UM without germline BAP1." (PMID 34771666, 2021). "Of the 7/38 (18%) UM with no BAP1 mutations, four patients had M3-UM and three had died from metastatic disease." (PMID 32340176, 2020). "Patients with a BAP1 mutation or absent BAP1 expression with immunohistochemistry (IHC) have a high metastatic risk while patients with an EIF1AX mutation have a low risk of metastatic disease." (PMID 33396957, 2020). "Moreover, intratumoral heterogeneity in metastatic tumors was minimal at protein expression of BAP1 and PBRM1." (PMID 28812986, 2017). "We observed inter-metastatic tumor heterogeneity of BAP1 in one (3%) patient." (PMID 28327121, 2017). "Third, we assessed whether loss of BAP1 and PBRM1 expression in metastatic tumors is associated with cancer-specific outcome." (PMID 28327121, 2017). "Further studies comparing the expression of BAP1, Survivin and EZH2 in different metastatic tumors and EM should be conducted." (PMID 34257556, 2021). "Eckel-Passow and colleagues analyzed the immunohistochemical expression of BAP1 and PBRM1 in primary and metastatic tumors from 97 patients." (PMID 34885018, 2021). "In contrast, another study showed that germline BAP1 mutations occur more often in metastatic ocular melanoma compared to nonmetastatic ocular melanoma, even though this difference was not significant and not adjusted for the greater risk of metastatic disease in BAP1-mutated UM in general." (PMID 33396957, 2020). "Replicate blocks were analyzed for BAP1 and PBRM1 expression in 12 metastatic tumors in order to investigate intra-tumor heterogeneity (median = 2, max = 5 replicate blocks per metastatic tumor)." (PMID 28327121, 2017). "BAP1 and PBRM1 staining was performed on longitudinal metastatic tumors for 32 patients (median = 2, max = 4 metastatic tumors per patient)." (PMID 28327121, 2017). "In our cohort of SPNs, we found that a lack of or reduced expression of both KDM6A and BAP1 is enriched in metastatic cases, suggesting that their function is a barrier to the development of metastatic disease at least in a subset of SPNs." (PMID 30306561, 2019). "These preclinical studies suggest that cordycepin may be effective in BAP1 mutant metastatic disease, for which no good therapies currently exist." (PMID 35804893, 2022). "The pathological and immunohistochemical findings in our case, including positive staining for calretinin, D2-40, CK7, BAP1, and WT1, and negativity for various other markers, confirmed the diagnosis of a benign cystic adenomatoid tumor and ruled out metastatic disease." (PMID 39479461, 2024).
metastatic disease (continued). "In contrast, BAP1 was absent, or downregulated, in the majority of poorly differentiated (grade III) specimens, whereas a statistically significant inverse correlation was observed between BAP1 staining and tumor grade, as well as progression to metastatic disease." (PMID 32541668, 2020).
malignant pleural mesothelioma (42 papers, 2014 to 2026). A malignant neoplasm that arises from mesothelial cells in the pleura and shows a diffuse growth pattern. "The inflammatory effect of BAP1 loss in the TME is also noticeable in malignant pleural mesothelioma, a cancer frequently mutated in BAP1." (PMID 41602827, 2026). "Recent research on survival rates revealed that individuals with germline BAP1 mutations and women with malignant pleural mesothelioma have better survival rates than males." (PMID 38671450, 2024). "Based on these results, Tazemetostat has been used in a phase-II study for the treatment of malignant pleural mesothelioma patients characterized by BAP1 [breast cancer 1 (BRCA1) associated protein 1] inactivation showing a good tolerability to the drug." (PMID 39680066, 2024). "Preoperative radiomic analysis of MR and CT images was successfully applied to differentiate isocitrate dehydrogenase and 1p19q mutations in glioma and BAP1 mutation in malignant pleural mesothelioma." (PMID 35251962, 2022). "The BAP1 gene mutation is the most frequent genomic alteration in malignant pleural mesothelioma; BAP1 orchestrates chromatin-associated processes, including gene expression, DNA replication and DNA repair." (PMID 35204459, 2022). "BRCA1‐associated protein‐1 (BAP1) expression is commonly lost in several tumors including malignant pleural mesothelioma (MPM)." (PMID 32944962, 2021). "By contrast, in malignant pleural mesothelioma, the presence of cytoplasmic BAP1 stain was associated with a favorable prognosis." (PMID 34771510, 2021). "Baseline and treatment characteristics of patients with malignant pleural mesothelioma in Group A (BAP1 inactivating mutation/copy number loss, n-8) and Group B (without a BAP1 alteration/not tested, n-37)." (PMID 33777745, 2021). "One gene that is often mutated in malignant pleural mesothelioma (MPM) is BRCA1-associated protein 1 (BAP1), a deubiquitinating enzyme with known tumor suppressor functions, and we observed that BAP1-proficient cells are more sensitive to RBM8A silencing." (PMID 34944051, 2021). "Similar findings have been reported from malignant pleural mesotheliomas, where BAP1 overexpression was also linked to aggressive tumor features or shortened survival." (PMID 31903168, 2019). "Between 23 and 64% of malignant pleural mesothelioma have somatic inactivating mutations in the BAP1 gene." (PMID 28756516, 2017). "Between 23 and 64% of malignant pleural mesotheliomas (MPMs) have somatic inactivating mutation in the BAP1 gene." (PMID 28756516, 2017). "A recent study has suggested that BAP1 inactivation is more closely associated with the epithelioid subtype of malignant pleural mesothelioma." (PMID 25952750, 2015). "BAP1 loss-of-function is increasingly reported in cancers including thoracic malignancies, with frequent mutation in malignant pleural mesothelioma." (PMID 25970771, 2015). "BAP1, a gene encoding a deubiquitinant enzyme, is mutated in several UM cases and in the malignant pleural mesothelioma (MPM), a human tumour found be associated with the Simian Virus 40 (SV-40) infection." (PMID 24886631, 2014). "BAP1 is a tumor suppressor gene expressed in normal tissues, showing nuclear denudation in >50% of malignant pleural mesothelioma and two-thirds of PMM cases." (PMID 39605894, 2024). "The nuclear deubiquitylase BRCA1-associated protein 1 (BAP1) is frequently inactivated in malignant pleural mesothelioma (MPM) and germline BAP1 mutation predisposes to cancers including MPM." (PMID 36669126, 2023). "In malignant pleural mesothelioma, a classic model of asbestos-related cancer, BAP1 has been reported as the most frequently altered gene, with a frequency ranging from 23% to 57% of cases." (PMID 35755315, 2022).
malignant pleural mesothelioma (continued). "As a very aggressive malignant tumor, malignant pleural mesothelioma (MPM) is believed to be closely related to asbestos exposure, BRCA1-associated protein 1 (BAP1) mutation and ionizing radiation to chest." (PMID 35664314, 2022). "Little is known regarding the outcomes of systemic treatments in BAP1-altered malignant pleural mesothelioma (MPM)." (PMID 33777745, 2021). "A recent review investigated the role of DNA damage in malignant pleural mesothelioma (MPM) where MPM seems to exhibit mutations in DDR at both the germline and somatic levels with frequent mutations in BRCA1 associated protein 1 (BAP1)." (PMID 33053746, 2020). "In particular BAP1 (+/-) mice exposed to low doses of asbestos developed malignant pleural mesothelioma (MPM) at a similar rate of BAP1+/+ mice exposed to 10 times higher doses." (PMID 32059499, 2020). "The marine drug lurbinectedin revealed an unprecedented efficacy against patient-derived malignant pleural mesothelioma cells, regardless of the histological type and the BAP1 mutation status." (PMID 34066159, 2021). "Although the number of models is too low to draw conclusions, olaparib might affect tumor growth independently of BAP1 status, as has been observed in malignant pleural mesothelioma." (PMID 31146482, 2019). "Furthermore, additional immunocytochemistry tests, such as BAP1 loss and p16 deletion may help distinguishing between benign pleural effusion and MPE, particularly benign mesothelial hyperplasia from malignant pleural mesothelioma." (PMID 38243259, 2024). "There have been reports of several cases of malignant pleural mesothelioma with no BAP1 gene mutation and with normal mRNA expression, which are negative for BAP1 protein staining, so post-translational events regulating instability might be responsible for BAP1 loss of function in such cases." (PMID 35204459, 2022). "In malignant pleural mesothelioma, BAP1 and YY1 cooperatively suppress the expression of DR4 and DR5 through the catalytic activity of BAP1." (PMID 33919439, 2021). "Tazemetostat showed a 54% disease control rate at week 12 for patients with BAP1-inactivated malignant pleural mesothelioma, with some partial responses observed but no confirmed complete responses." (PMID 39768352, 2024). "Tazemetostat was also recently evaluated for the treatment of patients with R/R malignant pleural mesothelioma with BAP1 inactivation (assessed as absence of nuclear BAP1)." (PMID 39403928, 2024).
renal carcinoma (41 papers, 2014 to 2025). A carcinoma arising from the epithelium of the renal parenchyma or the renal pelvis. "We showed that BAP1 gene mutation plus wild type PBRM1 had significant contributions to renal cancer PFS and DFS." (PMID 37515929, 2023). "Mutations in BAP1 (3p21.31) have been shown to be associated with poor cancer-specific survival in renal carcinoma." (PMID 37445575, 2023). "Loss of BAP1 leads to growth inhibition of renal cancer cells and enhances the effect of mesenchymal–epithelial transition." (PMID 36825082, 2023). "VHL is linked to key metabolic pathways in renal cancer as well as other tumor suppressor genes such as BRCA1-associated protein 1 (BAP1), which is required for normal kidney development and function." (PMID 37047552, 2023). "The age at which renal cancer is diagnosed is lower in individuals with a pathogenic variant in BAP1 with a range of between 32–80 years." (PMID 37607989, 2023). "Accordingly, the BAP1 mutation was selected for further investigations regarding its therapeutic potential in renal cancers." (PMID 35918352, 2022). "Our study predicted the prognosis of renal cancer patients by constructing a new immune score combined with the BAP1 mutation." (PMID 34733850, 2021). "The knockdown of SLC7A11 in UMRC6 cells (a BAP1-deficient renal cancer cell line) marginally affects cancer cell proliferation, suggesting that the BAP1-mediated tumor suppression through regulating SLC7A11." (PMID 32103754, 2020). "Loss of BAP1 promoted mesenchymal–epithelial transition process in renal cancer." (PMID 35935986, 2022). "Based on an analysis of 79 genes associated with renal cancer, we found that VHL, PBRM1, BAP1, SETD2, and TSC1 mutation rates were higher in all RCCs at 51%, 35%, 16%, 15%, and 13%, respectively." (PMID 37427096, 2023). "In renal cancer, SETD2 mutations are frequently associated with VHL, PBRM1, and BAP1 mutations as a result of chromosome 3p21 deletion." (PMID 37528416, 2023). "Given the reported age of onset of renal cancer in BAP1 carriers, starting from age 30 years reached consensus." (PMID 37607989, 2023). "As reported in our review, the most common somatic gene mutations in renal cancer are related to VHL, PBRM1, BAP1, and SETD2, although a relatively small number of other mutated genes are reported to be involved in kidney cancer." (PMID 36902045, 2023). "Our purpose was also to establish the role of BAP1 as a tumor suppressor protein in the tumorigenesis of renal cancer in the examined group of patients." (PMID 37445575, 2023). "BAP1 RNA expression was found to be significantly downregulated in ccRCC, while BAP1 protein level was the lowest in renal cancer." (PMID 35425712, 2022). "Knockout of BAP1 in HeLa cervical cancer and renal cancer cells exposed to ionising radiation resulted in increased cell death." (PMID 30669483, 2019). "In renal cancer, there are two other common subtypes, characterized by PBRM1 and BAP1 mutations." (PMID 39119581, 2024). "Renal cancers share immunogenicity and BAP1 aberrations with CM and UM." (PMID 35372013, 2022). "However, the regulatory mechanism of BAP1 on renal cancer angiogenesis remains to be further studied." (PMID 33761933, 2021). "BAP1/HCF-1 interaction is important for growth suppression in renal cancer; however, whether this is through BAP1-mediated deubiquitination and alteration of HCF-1 protein stability remains unclear." (PMID 30669483, 2019).
renal carcinoma (continued). "In addition, the high-risk group exhibited more variety of chromosome mutations and high mutant frequency of tumor suppressor BAP1, while knockdown of BAP1 inhibited tumorigenicity and lung metastasis; thus, the role of BAP mutations in the development of renal cancer needs to be further elucidated." (PMID 39247556, 2024). "We also collected the renal cancer tissue that was assessed for the expression of classical onco‐suppressor genes, downregulated in RCC, namely von Hippel–Lindau (VHL) Polybromo‐1 (PBRM1), SETD2, and BAP1." (PMID 39806854, 2025). "Although the prognostic impact of the PTEN and BAP1 mutations in renal carcinoma is under investigation, the prognostic significance of mutated PTEN and BAP1 genes has not ever been fully described in RCC." (PMID 37445575, 2023). "It is also a direct target of BAP1 and regulates cellular GSH levels in renal cancer cells." (PMID 37740028, 2023). "Most studies have identified the frequency of renal cancer in germline BAP1 carriers, and in many studies the type of renal cancers have not been histopathologically verified." (PMID 37607989, 2023). "Therefore, to ensure that the methylation changes seen across renal cancers were not due to the confounding effect of VHL and other mutations, we selected a group of pan-negative WT samples by excluding samples with VHL, BAP1, or PBRM1 mutations." (PMID 37528416, 2023). "Although we did find three VUS’s in BAP1 in three families and a pathogenic variant in MITF in one family, pathogenic germline variants in BAP1, MITF or CDKN2B are not frequent causes of hereditary renal cancer in Denmark." (PMID 31034483, 2019). "The results of the study indicate that germline variants in BAP1, MITF and CDKN2B are not frequent in Danish families with suspected hereditary predisposition to renal cancer, and in the families of this study a possible genetic background of RCC is still unresolved." (PMID 31034483, 2019).